IL25 (interleukin 25)
Diseases named in the same sentence as IL25 in open-access papers (continued):
Sharing a sentence is not in itself a finding about the gene and the disease.
Fulminant hepatitis (2 papers, 2019 to 2021). Acute hepatitis complicated by acute liver failure with hepatic encephalopathy occurring less than 8 weeks after the onset of jaundice. "Moreover, CCL17 was also reported to be a MDSC-attracting chemokine induced by IL-25 in D-galactose (D-Gal)/LPS-induced fulminant hepatitis (FH) mice." (PMID 34869447, 2021).
Gastric Metaplasia (2 papers, 2023 to 2024). Intestinal metaplasia of the gastric mucosa is an intermediate precancerous gastric lesion in the gastric cancer cascade from chronic gastritis and atrophy to dysplasia and adenocarcinoma. "Due to the established link between IL25 and IL13, as well as the functional requirement we established for tuft cells and ILC2s during gastric metaplasia and tumor growth, we next investigated the extent by which these cytokines promote epithelial growth." (PMID 37898600, 2023).
Giardia infection (2 papers, 2020 to 2021). "The effects of a Giardia-infection on the expression levels of IL-25 (IL-17E) and the alarmin IL-33 have, to our knowledge, never been studied." (PMID 32283818, 2020).
immune-deficiency (2 papers, 2018 to 2024). "CNV identified our previously reported interleukin 25 amplification in the proband; however, the variant was not validated to be a candidate gene for immunodeficiency." (PMID 29556235, 2018).
inflammatory disorders of the skin (2 papers, 2022 to 2025). "As per previous reports, IL-17E can actively participate in T-helper type 2 immune responses in the lungs and gut however, recent reports observed that IL-17E/IL-25 actively participates in several inflammatory disorders of the skin." (PMID 36298704, 2022).
intestinal infections (2 papers, 2019 to 2025). "Collectively, these data position IL-25-induced eosinophil responses as a key element in preserving epithelial barrier function and resolving tissue inflammation during intestinal infections." (PMID 40860650, 2025). "The IL-1β secretion, which controls the innate cytokines IL-25 and IL-33 production, both critical for the Th2 promotion, has been proposed as a mechanism to assure the chronicity of the parasite in intestinal infections by nematodes." (PMID 30967874, 2019).
intestinal parasite infection (2 papers, 2019 to 2024). "A major driver of the ILC2 response following intestinal parasite infection has been identified as the tuft cell, which produces IL-25 promoting ILC2 expansion and IL-13 production." (PMID 31730667, 2019). "nILC2 locates at barrier tissues which are crucial for tissue homeostasis and primarily IL-33-responsive, while iILC2 is not resided in peripheral tissues in the steady state but can be elicited at many sites by intestinal parasite infection or IL-25/IL-33 treatment." (PMID 39559705, 2024). "The extent of functional redundancy between IL-33 and IL-25 for intestinal parasitic infections is still unclear, but experiment evidence indicated that IL-33 and IL-25 may largely exert a co-operative action." (PMID 39559705, 2024).
intestinal tumor (2 papers, 2022). "While IL-25-deficiency led to a decrease in both intestinal tumor number and size, IL-33-deficiency in our study only reduced tumor number and not tumor size, in keeping with them mediating separate pro-tumorigenic pathways." (PMID 35658010, 2022). "In Apc1322T/+ mice, genetic deficiency of IL-25 reduced intestinal tumour burden and virtually doubled survival, and antibody-mediated blockade of IL-25-signalling similarly reduced CRC." (PMID 36263033, 2022). "S4A), and crossed it with Apc1322T/+ mice to allow detection of the tomato fluorescent protein as a surrogate for intestinal tumor Il25 expression." (PMID 35658010, 2022). "Conversely, modulation of IL-25-signaling affected intestinal tumor ILC2s, while mast cells and Tregs were unaffected." (PMID 35658010, 2022). "Deletion of RORα in adaptive T cells did not affect intestinal tumor burden, and exogenous IL-25 treatment in ILC2-replete and ILC2-deplete mice showed that ILC2s are essential for IL-25-mediated intestinal tumorigenesis." (PMID 35658010, 2022). "We found that intestinal tumor ILC2s had increased expression of IL-25R, but did not express ST2, and while the pro-tumoral effects of IL-25 required ILC2s, IL-33 acted independently of ILC2s correlating instead with mast cell and Treg expansion." (PMID 35658010, 2022).
itch (2 papers, 2022 to 2025). "Keratinocytes also release IL-25 as a third epithelial alarmin; IL-25 strengthens type 2 immunity and links epithelial injury with itch through PAR2 pathways." (PMID 41479908, 2025). "The inhibition of JAK ensures the inhibition of receptors; therefore, the subsequent biological effects, from a greater number of cytokines, are variably involved in the pathogenesis of pruritus, not only IL13 and IL4 but also IL31, IL2, IL8, IL25, IL33, IFNγ and thymic stromal lymphoprotein (TSLP)." (PMID 35890180, 2022).
liver diseases (2 papers, 2020 to 2022). "Moreover, we demonstrated that IL-33 has an inhibitory effect on IL-25-mediated IL-17A expression in hepatic ILC2, indicating that in IL-33-triggered liver diseases, the development of inflammatory ILC2 might be suppressed." (PMID 31974518, 2020).
oropharyngeal cancer (2 papers, 2020 to 2025). Carcinoma, predominantly squamous cell, arising from the epithelial cells of the oropharynx. "IL-17A, IL-17E/IL-25, IL-17F, and TNF-α, and their association with disease advancement in patients with oral and oropharyngeal cancer." (PMID 40723410, 2025). "The concentrations of IL-17A, IL-17F, IL-17E/IL-25, and TNF-α in saliva samples in the patients diagnosed with oral and oropharyngeal cancer was correlated with the disease stage as well as with T, N, and M parameters separately." (PMID 32855976, 2020). "The aim of this study was to assess levels of IL-17A, IL-17E/IL-25, IL-17F, and TNF-α in the saliva in patients with oral and oropharyngeal cancer, depending on the degree of malignancy and bacteriological cultures from the oral cavity as potential biomarkers of cancer." (PMID 32855976, 2020).
peanut allergy (2 papers, 2013 to 2022). "In conclusion, this study is the first to show that IL-25 is highly elevated in a subgroup of peanut-allergic children and suggests a role for IL-25 in the development and/or persistence of peanut allergy, in this subgroup." (PMID 24295226, 2013). "Increased duodenal levels of Il-25 was found in peanut allergy in a mouse study." (PMID 24295226, 2013). "This suggests a role for IL-25 in the pathogenesis of peanut allergy and elevated plasma IL-25 may be a sign of a severe atopic phenotype." (PMID 24295226, 2013). "However, the data do demonstrate that plasma IL-25 was only present in children with ongoing peanut allergy and, importantly, despite a peanut-free diet for at least 6 months." (PMID 24295226, 2013). "Murine studies revealed that increased epithelial IL33 secretion is sufficient for in vivo DC activation leading to peanut allergy, independent of IL25 and TSLP." (PMID 36700233, 2022).
prostate carcinoma (2 papers, 2021 to 2023). A carcinoma that arises from epithelial cells of the prostate gland. "In aggressive grades of prostate cancer, it has also been shown that the level of IL‐25 was decreased." (PMID 34128588, 2021). "Tuft cells in mouse models of prostate cancer express Il25, and Il10 that may have immunosuppressive roles, as well as enzymes for eicosanoid synthesis for production of other immunomodulatory molecules." (PMID 37386128, 2023). "In this regard, expression of IL‐25 and IL‐25R in prostate cancer tissue samples of prostate cancer reversely correlated to Gleason grade, suggesting that IL‐25 might be involved in the pathogenesis." (PMID 34128588, 2021). "Although there is no defined underlying mechanism concerning IL‐25’s role in prostate cancer, it is proposed that IL‐25 interaction with IL‐25R might exert an antitumor function." (PMID 34128588, 2021).
systemic sclerosis (2 papers, 2014 to 2015). A chronic disorder, possibly autoimmune, marked by excessive production of collagen which results in hardening and thickening of body tissues. "IL-25 has been implicated in both experimental models of fibrosis and has been detected in samples from patients with chronic lung conditions and in the skin of patients with systemic sclerosis." (PMID 26635811, 2015).
urticaria (2 papers, 2024). A vascular reaction of the skin characterized by erythema and wheal formation due to localized increase of vascular permeability. "The cytokines promoting a Th2 profile, such as IL-33 and IL-25 in association with vasoactive agents (e.g., VEGF), are identified in urticaria lesions, but not in healthy skin." (PMID 38541037, 2024).
acid reflux (1 paper, 2025). "This may indicate that while IL-25 may not be involved in the pathogenesis of GERD, the components of non-acid reflux may have some role in its induction." (PMID 40981017, 2025).
acute lung injury (1 paper, 2019). A condition of lung damage that is characterized by bilateral pulmonary infiltrates (pulmonary edema) rich in neutrophils, and in the absence of clinical heart failure. "After the injury, lung epithelial secreted IL-25 promotes TNF-α production in macrophage leading to acute lung injury (ALI)." (PMID 31340864, 2019).
Airway obstruction (1 paper, 2022). Obstruction of conducting airways of the lung. "IL-25 stimulates type 2 inflammation and contributes to airway obstruction by triggering bronchoconstriction, mucus production, and infiltration of inflammatory cells into airways." (PMID 35508632, 2022).
allergic conjunctivitis (1 paper, 2024). "Because of the involvement of IL-25 in the pathophysiology of allergic conjunctivitis, targeting IL-25 or IL-25R on effector cells is a potential modality for attenuating IL-25 mediated type 2 immune response." (PMID 38541674, 2024).
allergic contact dermatitis (1 paper, 2019). An inflammatory skin condition caused by an immune response to direct contact between the skin and an allergen. "Like in allergic contact dermatitis, IL-25 proteins were hardly detectable in aortae of Il1rn−/− mice (12 weeks) by immunofluorescence using anti-IL-25 Ab (data not shown)." (PMID 31745167, 2019).
aortitis (1 paper, 2019). Inflammation of the aorta. "In association with this, the aortitis severity score and the aortic inflamed area were significantly smaller in Il25−/−Il1rn−/− mice compared with Il1rn−/− mice." (PMID 31745167, 2019). "Our findings improve our understanding of the molecular mechanisms involved in development of aortitis and suggest that neutralization of IL-25 may be a potential therapeutic target for aortitis." (PMID 31745167, 2019). "Indeed, the incidence of aortitis in Il25−/−Il1rn−/− mice was significantly lower than in Il1rn−/− mice." (PMID 31745167, 2019). "In our model, IL-25 deficiency resulted in reduced expression of Il17a and Tnfa mRNA in the aortae of Il1rn−/− mice, suggesting that IL-25 somehow enhanced the development of IL-1–, TNF– and IL-17–mediated aortitis in Il1rn−/− mice." (PMID 31745167, 2019). "Our findings suggest that neutralization of IL-25 may be a potential therapeutic target for aortitis." (PMID 31745167, 2019). "Therefore, IL-17B may have a compensatory role in induction of type 3 immune responses in the aortitis of Il25−/−Il1rn−/− mice." (PMID 31745167, 2019). "In the present study, we demonstrated that IL-25 is crucial for development of IL-1–, TNF– and IL-17–mediated aortitis in Il1rn−/− mice." (PMID 31745167, 2019). "Here, we demonstrate that IL-25 plays a facilitative role in the development of IL-1–, TNF– and IL-17A–mediated aortitis in Il1rn−/− mice." (PMID 31745167, 2019). "We found that expression of II25 mRNA was increased in the aortae of Il1rn−/− mice, suggesting that IL-25 may suppress development of IL-1–, TNF– and IL-17A–dependent aortitis in Il1rn−/− mice by inhibiting type 3-mediated immune responses." (PMID 31745167, 2019). "We found that expression of Il25 mRNA was significantly increased in the aortae of Il1rn−/− mice compared with wild–type mice and Il25−/−Il1rn−/− mice (as a negative control), suggesting involvement of IL-25 in the development of aortitis." (PMID 31745167, 2019). "However, the role of IL-25 in IL-1–, TNF– and IL-17A–mediated aortitis in Il1rn−/− mice has been unclear." (PMID 31745167, 2019). "The development of aortitis was attenuated, but not completely abrogated, in Il25−/−Il1rn−/− mice compared with Il1rn−/− mice." (PMID 31745167, 2019). "Tissue–, but not immune cell–, derived IL-25 was crucial for development of aortitis." (PMID 31745167, 2019). "IL-25 enhanced IL-1β and TNF production by IL-25 receptor–expressing dendritic cells and macrophages, respectively, at inflammatory sites of aortae of Il1rn−/− mice, contributing to exacerbation of development of IL-1–, TNF– and IL-17A–dependent aortitis in those mice." (PMID 31745167, 2019). "Il1rn−/− mice transferred with Il25−/−Il1rn−/− BM cells developed aortitis similarly to Il1rn−/− mice transferred with Il1rn−/− BM cells, indicating that IL-25 produced by BM cell–derived immune cells was not essential for development of aortitis in Il1rn−/− mice." (PMID 31745167, 2019). "Regarding this, using bone marrow cell transfer analysis, we showed that IL-25 derived from non-hematopoietic cells rather than immune cells was crucial for development of IL-1–, TNF– and IL-17–mediated aortitis in Il1rn−/− mice." (PMID 31745167, 2019). "However, Il25−/−Il1rn−/− mice showed attenuated development of aortitis compared with Il1rn−/− mice, indicating that IL-25 contributed to exacerbation—not suppression—of IL-1–, TNF– and IL-17–mediated aortitis in Il1rn−/− mice." (PMID 31745167, 2019). "On the other hand, our results suggest that IL-25 may enhance production of IL-6, IL-17A and TNF, but not IL-23, thereby contributing to development of IL-1–, TNF– and IL-17A–dependent aortitis in Il1rn−/− mice." (PMID 31745167, 2019).
avian influenza (1 paper, 2025). Infection of domestic and wild fowl and other birds with influenza A virus. "Immune genes, such as interleukins IL6, IL12B, and IL25, located in the introgressed regions, play a crucial role in the immune response to most low pathogenic avian influenza strains." (PMID 39965774, 2025).
bronchiectasis (1 paper, 2019). Segmental, irreversible dilation of the bronchial tree resulting in the accumulation of secretions which leads to obstruction. "It was reported that Citrobacter are involved in the antagonized effect of IL-17 on IL-25-mediated airway inflammation, while the reduction of Pseudomonas might be closely related to the alleviation of bronchiectasis." (PMID 31466312, 2019).
brucellosis (1 paper, 2021). Brucellosis is a bacterial infection that spreads from animals to people via unpasteurized dairy products or by exposure to contaminated animal products or infected animals. "We investigated the expression of IL-25, IL-17RB, Th2-LCR lncRNA, and TRAF3IP2, which play roles in brucellosis." (PMID 35071039, 2021). "Thus, this work focused on the expression of four Th2 and Th17 immunity-related factors (Th2-LCR lncRNA, IL-25, TRAF3IP2, and IL-17RB) in different stages of brucellosis." (PMID 35071039, 2021).
cholangiocarcinoma (1 paper, 2021). A carcinoma that arises from the intrahepatic biliary tree (intrahepatic cholangiocarcinoma) or from the junction, or adjacent to the junction, of the right and left hepatic ducts (hilar cholangiocarcinoma). "Moreover, survival analysis discovered that upregulation of IL‐25 was associated with shorter survival time in cholangiocarcinoma patients." (PMID 34128588, 2021). "Further analysis regarding IL‐25 involvement in cholangiocarcinoma using protein interaction software STITCH has shown that IL‐25 has potential direct and indirect interaction with SMAD2, TGF‐β1, NF‐κB, and SNAI." (PMID 34128588, 2021). "Although these interactions have not been verified experimentally, it is proposed that IL‐25 is associated with these factors to mediate EMT in cholangiocarcinoma." (PMID 34128588, 2021).
chronic asthma (1 paper, 2015). An asthma that is characterized by the development of persistent airway inflammation and recurrent attacks of breathlessness and wheezing, which vary in severity and frequency. "Consequently we set out to extend our previous studies to examine the direct effects of IL-25 alone on the production of these mediators in the airways in vivo in our murine model of chronic asthma." (PMID 25889697, 2015).
Chronic Obstructive Asthma (1 paper, 2023). Chronic airway obstruction caused by asthma. "IL-25 blocking therapy may serve the potential paradigm for the treatment of chronic obstructive asthma." (PMID 37635231, 2023).
cognitive decline (1 paper, 2021). "In the aMCI group, higher baseline plasma levels of IL-2, sCD40L, and VEGF were associated with a lower cognitive decline, and in the AD group, higher baseline plasma levels of IFNγ, IL-5, IL-17A, IL-25, FGF, GM-CSF, and VEGF were associated with a more rapid cognitive decline." (PMID 34122046, 2021). "Higher baseline levels of IL-2, sCD40L, IL-8, and VEGF were associated with a lower annual cognitive decline in the aMCI group, and higher baseline levels of Aβ1–40, IFNγ, IL-5, IL-17A, IL-25, and FGF were associated with a rapid annual cognitive decline in the AD group." (PMID 34122046, 2021). "In contrast, the AD group showed that the higher baseline levels of IFNγ (r = −0.701, p = 0.036), IL-5 (r = −0.756, p = 0.019), IL-17A (r = −0.759, p = 0.021), IL-25 (r = −0.840, p = 0.036), and FGF (r = −0.780, p = 0.013) were significantly correlated with more rapid cognitive decline." (PMID 34122046, 2021).
colorectal adenocarcinoma (1 paper, 2022). The most common type of colorectal carcinoma. "Here, we found that sustained innate IL-25 and ILC2 signals helped to maintain a cancer-permissive microenvironment in intestinal polyps and colorectal adenocarcinoma, by preventing anti-tumoral T cell and IFNγ-mediated immunity." (PMID 35658010, 2022).
emphysema (1 paper, 2013). "Regarding other ligands for IL17RA, IL-25 has been reported to be associated with both Th2 and Th17 immune responses, however, little is known about the role of this cytokine in emphysema development." (PMID 23331548, 2013).
endotoxemia (1 paper, 2021). "It is also important to consider that IL-25 protects against LPS-induced lethal endotoxemia in such a way that there could be a regulation between these cytokines in inflammatory processes associated with the presence of LPS." (PMID 34443554, 2021).
enterocolitis (1 paper, 2024). An inflammatory process affecting the small intestine and colon. "IL-17f was associated with both dermatologic and enterocolitis irAEs, while IL-25 was elevated in enterocolitis irAEs (P < 0.05)." (PMID 39403935, 2024).
epilepsy (1 paper, 2020). A brain disorder characterized by episodes of abnormally increased neuronal discharge resulting in transient episodes of sensory or motor neurological dysfunction, or psychic dysfunction. "Elevations in IL-25 have been observed in cortical and hippocampal tissues of patients with epilepsy." (PMID 32804078, 2020).
gastric tumor (1 paper, 2023). "Together this data leads us to conclude that gastric tuft cells and ILC2s, like their intestinal counterparts, are the primary source of IL25 and IL13 during SPEM and gastric tumor development." (PMID 37898600, 2023). "Because of the limited antigenicity of the gastric tumors in gp130F/F mice and our inability to detect IL13- or IL25-responsive MDSCs in these tumors, we cannot exclude an indirect contribution of IL25 signaling via MDSCs or IL13 produced by T cells to GC development." (PMID 37898600, 2023).